ELSPBP1 (epididymal sperm binding protein 1)
Description:
Binds to spermatozoa upon ejaculation and may play a role in sperm capacitation. Has phosphorylcholine-binding activity (By similarity).
Synonyms: hE12; E12; EDDM12; EL149
Tractability: Antibody: UniProt places it where antibodies can reach, with high confidence; UniProt predicts a signal peptide or a membrane-spanning region; its Gene Ontology location is reachable by antibodies, with medium confidence.
Gene: Protein-coding gene on chromosome 19 (47,994,632 to 48,025,154, forward strand). Ensembl gene ENSG00000169393.
Subcellular location: Secreted
Gene Ontology:
Molecular function: heparin binding
Biological process: sperm capacitation
Cellular component: cell surface; non-collagenous component of interstitial matrix; extracellular region
Genetic constraint (gnomAD): Loss-of-function variants: 38 observed, 33.96 expected, observed/expected ratio (o/e) 1.12, 90% interval 0.86 to 1.47. The upper end of that interval is the gene's LOEUF score, 1.47, which puts it in group 6 of 6, group 1 being the genes least tolerant of losing a copy. Missense variants: 267 observed, 274.12 expected, observed/expected ratio (o/e) 0.97, 90% interval 0.88 to 1.08. Synonymous variants: 85 observed, 98.92 expected, observed/expected ratio (o/e) 0.86, 90% interval 0.72 to 1.03.
Homologues: Orthologues: macaque ELSPBP1 (97% identical), chimpanzee ELSPBP1 (94% identical), pig ELSPBP1 (79% identical), dog ELSPBP1 (77% identical). Paralogues in human: BSPH1 (17% identical).
Diseases named in the same sentence as ELSPBP1 in open-access papers:
ELSPBP1 is named in the same sentence as 1 disease in open-access papers, as found by Europe PMC text mining. Sharing a sentence is not in itself a finding about the gene and the disease.
ELSPBP1 shares sentences with these, for which no sentence is quoted: Infertility (1 paper).